RNU6-573P (RNA, U6 small nuclear 573, pseudogene)
Gene: Small nuclear RNA gene on chromosome 4 (35,495,898 to 35,496,003, forward strand). Ensembl gene ENSG00000206665.
Homologues: Orthologues: chimpanzee U6 (100% identical), macaque U6 (93% identical), guinea pig U6 (80% identical), dog U6 (75% identical). Paralogues in human: RNU6-1011P (88% identical), RNU6-949P (88% identical), RNU6-1060P (87% identical), RNU6-125P (87% identical), RNU6-15P (87% identical), RNU6-266P (87% identical), RNU6-1042P (86% identical), RNU6-12P (86% identical), RNU6-13P (86% identical), RNU6-166P (86% identical), RNU6-26P (86% identical), RNU6-31P (86% identical), and 1286 more.